PTPRE (protein tyrosine phosphatase receptor type E)
Description:
Isoform 1 plays a critical role in signaling transduction pathways and phosphoprotein network topology in red blood cells. May play a role in osteoclast formation and function (By similarity). Isoform 2 acts as a negative regulator of insulin receptor (IR) signaling in skeletal muscle. Regulates insulin-induced tyrosine phosphorylation of insulin receptor (IR) and insulin receptor substrate 1 (IRS-1), phosphorylation of protein kinase B and glycogen synthase kinase-3 and insulin induced stimulation of glucose uptake (By similarity). Isoform 1 and isoform 2 act as a negative regulator of FceRI-mediated signal transduction leading to cytokine production and degranulation, most likely by acting at the level of SYK to affect downstream events such as phosphorylation of SLP76 and LAT and mobilization of Ca(2+).
Synonyms: R-PTP-epsilon; PTPE; HPTPE
Tractability: Small molecule: a high-quality ligand is known. Antibody: its Gene Ontology location is reachable by antibodies, with high confidence; UniProt places it where antibodies can reach, with medium confidence; UniProt predicts a signal peptide or a membrane-spanning region. PROTAC: ubiquitination databases record sites on it; its protein half-life has been measured; a small molecule that binds it is known.
Target class: Enzyme; Protein Phosphatase; Receptor tyrosine-protein phosphatase; Tyrosine protein phosphatase; Phosphatase
Gene: Protein-coding gene on chromosome 10 (127,906,805 to 128,085,856, forward strand). Ensembl gene ENSG00000132334.
Subcellular location: Cell membrane (Isoform 1); Cytoplasm (Isoform 2); Cytoplasm (Isoform 3)
Subcellular location (Human Protein Atlas): Intermediate filaments
Gene Ontology:
Molecular function: protein binding; protein tyrosine phosphatase activity; transmembrane receptor protein tyrosine phosphatase activity; identical protein binding
Biological process: negative regulation of insulin receptor signaling pathway; protein dephosphorylation; signal transduction; regulation of mast cell activation
Cellular component: cytoplasm; nucleus; plasma membrane
Genetic constraint (gnomAD): Loss-of-function variants: 50 observed, 99.64 expected, observed/expected ratio (o/e) 0.5, 90% interval 0.4 to 0.63. The upper end of that interval is the gene's LOEUF score, 0.63, which puts it in group 2 of 6, group 1 being the genes least tolerant of losing a copy. Missense variants: 732 observed, 928.1 expected, observed/expected ratio (o/e) 0.79, 90% interval 0.74 to 0.84. Synonymous variants: 345 observed, 354.97 expected, observed/expected ratio (o/e) 0.97, 90% interval 0.89 to 1.06.
Homologues: Orthologues: chimpanzee PTPRE (99% identical), macaque PTPRE (99% identical), dog PTPRE (95% identical), guinea pig PTPRE (94% identical), rat Ptpre (93% identical), pig PTPRE (90% identical), mouse Ptpre (86% identical), tropical clawed frog ptpre (80% identical), zebrafish ptprea (73% identical), zebrafish ptpreb (72% identical). Paralogues in human: PTPRA (66% identical), PTPRS (46% identical), PTPRD (46% identical), PTPRF (45% identical), PTPRM (36% identical), PTPRC (36% identical), PTPRK (35% identical), PTPRT (35% identical), PTPRZ1 (33% identical), PTPRG (33% identical), PTPRU (32% identical), PTPRJ (21% identical), and 23 more.